IL10 (interleukin 10)
Diseases named in the same sentence as IL10 in open-access papers (continued):
Sharing a sentence is not in itself a finding about the gene and the disease.
helminth infections (continued). "The overexpressed cytokines IL-10 and TGF-β could lead to immunological tolerance and certain types of damage in the host, but at the same time, they could prevent the expulsion of worms, thereby promoting chronic helminth infections." (PMID 36016178, 2022). "Although the observed results could be due to an incomplete blockade of IL-10R, it is worth mentioning that, according to other ascariasis or helminthiasis studies, IL-10 is not essential for host immunosuppression." (PMID 31611876, 2019). "Finally, although CD4+ TRM cells can produce IFNγ/IL-17, and IL-4/IL-13 following helminth infection, their production of IL-10 has not previously been reported." (PMID 25974019, 2015). "Later, by the same authors, disproved that reduction in TH1 cytokines response during chronic helminth infection might not be only due to TH1/TH2 shift but due to increased secretion of Treg cell cytokines (IL-10 and TGF-β)." (PMID 24710174, 2014). "In addition, while IL-10 also appears to play an important role in down modulation of Th1 responses in active TB individuals without helminth infection, this effect appears to be selective to mono- functional Th1 cells only." (PMID 25211342, 2014). "Some studies investigating T cell responses following various helminth infections have also previously reported induction of both classical FOXP3+IL-10+ and non-conventional FOXP3-IL-10+ regulatory T cells." (PMID 35720355, 2022). "The cytokine profile also confirmed that rTsPmy-pulsed DCs stimulated T. spiralis-infected mouse CD4+ cells to secrete IL-4, IL-10, TGF-β and IL-17A, but not IFN-γ, consistent with the Th2-skewed immune response induced by helminth infections." (PMID 27809931, 2016). "We analyzed IFN-γ, IL-5 and IL-10 secreting cells from a subset of 30 HIV negative TB patients and 56 CCs with and without helminth infection." (PMID 26248316, 2015).
Crohn disease (164 papers, 2005 to 2026). A gastrointestinal disorder characterized by chronic inflammation involving all layers of the intestinal wall, noncaseating granulomas affecting the intestinal wall and regional lymph nodes, and transmural fibrosis. "Linear regression models revealed significant associations between salivary IL-6 and IL-10 with Crohn’s disease; however, those associations were diminished after adjusting the model for age, DMFT, BOP%, and medication use." (PMID 38246944, 2024). "Patients carrying loss-of-function IL-10 or IL-10R mutations are at a high risk of Ulcerative colitis (UC) and Crohn’s disease (CD), IBD syndromes which involve chronic inflammation of the gut." (PMID 36110841, 2022). "Lactococcus lactis (LL-Thy12), in which the thymidylate synthase gene was replaced with a synthetic sequence encoding mature human interleukin-10, was found to alleviate Crohn’s disease." (PMID 35811664, 2022). "Several pieces of evidence from previous studies revealed that IL-4 and IL-10 depletion is associated with pronounced ulcerative colitis and Crohn’s disease, type 2 diabetes, metabolic syndrome." (PMID 36569878, 2022). "Of note, even in the IL-10-deficient mouse model mimicking severe infantile Crohn’s disease associated with IL-10 loss of function, colitogenic CD4+ T lymphocytes conserve their analgesic activity." (PMID 34299013, 2021). "Our study has several unique features, most notably the use of highly susceptible GF 129SvEv IL10−/− mice colonized as young adults with human complex microbiota by transplanting pooled feces from patients with active Crohn’s disease or ulcerative colitis." (PMID 34684567, 2021). "Among immune-related genes associated with Crohn’s disease, those involving the IL-10 regulatory pathway are associated with severe forms of the disease." (PMID 34299013, 2021). "For instance, genetic variants in the IL-10 and IL-10R loci are only found associated with Crohn's disease, which is striking given the importance of IL-10 regulatory function in the intestinal barrier as well as in inducing IgA class switch." (PMID 30915067, 2019). "Patients with CARD8 mutations and excessive IL-1β production leading to Crohn's disease are in principle similar to patients with IL-10 abnormalities since in both cases increased NLRP3 inflammasome hyperactivity is due to lack of an inflammasome inhibitor." (PMID 30455704, 2018). "Several other genes such as ORMDL3 and IL-10 have also been associated with both T1D and Crohn's disease." (PMID 26734582, 2015). "A human study reported that IL-10 supplementation is associated with increased risks of hyperferritinemia and anemia in Crohn’s disease patients." (PMID 26646112, 2015). "Previously, we reported that low IL-10 mRNA levels in intestine are associated with a poor response to glucocorticoids in active Crohn’s disease." (PMID 26090671, 2015). "It is important to highlight that the clinical benefit of G-CSF therapy in Crohn's disease patients is thought to be related to its ability to induce IL-10-mediated regulatory functions, associated possibly with increased pDCs numbers in the inflamed gut." (PMID 24319468, 2013). "Exposure of IL-10 deficient mice (BALB/c-background) to normal microbiota provoked enterocolitis (mimics Crohn’s disease)." (PMID 23761791, 2013). "In fact, it was recently demonstrated that the Crohn’s-disease-associated NOD2 mutation suppresses human IL-10 transcription by inhibiting the activity of the nuclear ribonucleoprotein hnRNP-A1." (PMID 23162548, 2012). "Some studies have shown that human Crohn's disease associated “loss-of-function” mutations in Nod2 show reduced transcription of IL-10 in response to bacteria." (PMID 21387014, 2011). "An extensive genomic analysis of the IL-10 gene and flanking regions of 94 Ulcerative colitis and 94 Crohn disease patients revealed polymorphisms in the IL-10 coding gene, of which one (R159) was in the receptor binding site, as reported by Josephson." (PMID 21464967, 2011).
Crohn disease (continued). "We examined the relationship between IL-10 and Th17 cells in patients with Crohn's disease and in IL-10-deficient (IL-10-/-) mice." (PMID 22176654, 2011). "Odds ratios and 95% confidence intervals (OR (CI)) for associations between IL-10 gene polymorphisms and ulcerative colitis (UC) or Crohns disease (CD) in selected case-control studies." (PMID 20509889, 2010). "For instance, mRNA-encoding for interleukin-10 (IL-10), an anti-inflammatory cytokine, could be delivered to immune cells to help control inflammation in diseases like Crohn’s disease or ulcerative colitis." (PMID 39598489, 2024). "This might be due to patchy colonic inflammation associated with the Crohn’s disease-like phenotype reported in IL-10−/− mice." (PMID 38918576, 2024). "Indeed, high-dose IL-10 treatment in patients with endotoxemia or Crohn’s disease was associated with undesired pro-inflammatory effects by enhancing the production of other pro-inflammatory cytokines, such as IFN-γ." (PMID 37283736, 2023). "The failure to identify associations between IL10 variants and more common forms of Crohn’s disease may be explained by the current limitations of NGS bioinformatics analysis." (PMID 33849446, 2021). "Interleukin-10 (IL-10) deficient mice spontaneously develop IBD when exposed to the normal gut microbiota from their control wild type background to provoke enterocolitis similar to Crohn’s disease." (PMID 28587181, 2017). "Overall, the frequency for carriers of shorter GTn repeats in intron 2 of the TLR2 gene, which have previously been associated with low TLR2 expression and high IL-10 production, was slightly elevated in Crohn’s disease and ulcerative colitis compared to healthy controls (16.0% resp." (PMID 28388655, 2017). "Furthermore, significant associations of variants at the IL10 locus with Crohn’s disease and UC in genome-wide association studies support the role of IL10 signalling in contributing to polygenic risk of disease." (PMID 27003245, 2016). "In conclusion, we hypothesize that IL-10 treatment is associated with increased prohibitin and would decrease inflammation and fibrosis in an animal model of Crohn's disease." (PMID 23690666, 2013). "The urinary and plasma metabolite profile of an interleukin 10 deficient mouse model (IL-10 −/−) of Crohn’s disease revealed alterations in metabolic pathways that could be related to intestinal inflammation." (PMID 23800341, 2013). "Importantly, 4 of these candidate genes are key in pathways relevant in the context of human Crohn’s disease (FcgR1, Vav3, Vcam1 and Ctss), a disease with highly similar pathology to both the IL10 deficient and T. muris models of colonic inflammation." (PMID 23442222, 2013). "Moreover, some subsets of Crohn’s disease patients are actually deficient in the production of IL-10, and therefore in this subset this probiotic therapy may be of limited use." (PMID 22681958, 2012). "Notably, researchers have found that IL-1α/IL-1β and IL-10 are critical regulators of monocyte IL-23 production, distinguishing homeostatic IL-23 production from inflammation-associated IL-23 production in patients with severe ulcerative active Crohn’s disease." (PMID 40564117, 2025). "Patients with Crohn’s disease, who were administered high doses of IL-10, experienced increased inflammation due to elevated levels of Interferon-gamma (IFN-γ)." (PMID 40761632, 2025). "In the context of using IL-10 to treat Crohn’s disease, it has been observed that IL-10 induces the pro-inflammatory cytokine IFN-γ." (PMID 39000453, 2024). "Knockout studies have suggested that interleukin-10 acts as an essential immunoregulator in the intestinal tract: in fact, patients with Crohn’s disease react favorably to treatment with recombinant interleukin-10 producing bacteria." (PMID 35409057, 2022). "Direct supplementation of rhIL-10 protein has been shown to alleviate the symptoms of IBD in both IL-10 KO mice and patients with Crohn’s disease." (PMID 36110841, 2022).
Crohn disease (continued). "Despite the appealing therapeutic potential of IL‐10, clinical trials assessing its therapeutic efficacy in Crohn's Disease (CD) have been disappointing to date, probably due to the very short half‐life." (PMID 36169258, 2022). "Subcutaneous IL-10 administered daily for 28 days to patients with mild to moderately active Crohn’s disease was found to be safe, well-tolerated, and showed clinical and endoscopic intestinal improvement." (PMID 36148228, 2022). "A CB2 receptor agonist has also been shown to induce Treg cells and IL-10 in a murine model of Crohn’s disease." (PMID 35185546, 2021). "IL-10-KO mice develop Th1 type chronic colitis, which has similar symptoms as Crohn’s disease in humans." (PMID 32636750, 2020). "Previous studies with patients suffering from Crohn’s disease have reported subcutaneous therapy with recombinant IL-10 to be safe in humans." (PMID 32937823, 2020). "Certain TNF-α and IL-10 haplotypes were associated with a higher production of TNF-α and IL-10 in Crohn’s disease and ulcerative colitis, possibly explaining the differences observed in baseline target concentrations and response observed in patients." (PMID 31817205, 2019). "The human colonic mucosa contains regulatory type 1-like (Tr1-like, i.e., IL-10-secreting and Foxp3-negative) T cells specific for the gut Clostridium Faecalibacterium prausnitzii (F. prausnitzii), which are both decreased in Crohn's disease patients." (PMID 30787928, 2019). "We further demonstrated that GSK2256294, a clinical EPHX2i, reduced the production of IL2, IL12p70, IL10 and TNFα in both ulcerative colitis and Crohn's disease patient-derived explant cultures." (PMID 31002701, 2019). "Bacteroides uniformis, a Treg and IL10 inducer that has been found to be reduced in patients with Crohn’s disease, is also reduced with MSM in our donors and recipients." (PMID 30947289, 2019). "A recent study investigated the effect of glyburide in IL10−/− spontaneous Crohn’s disease mouse model." (PMID 29872077, 2018). "Systemic administration of recombinant human IL-10 produced in Escherichia coli has been studied in Phase II clinical trials to treat patients with Crohn's disease." (PMID 29682323, 2018). "In studies in Crohn’s disease with human IL-10 treatment, higher dose IL-10 treatment led to elevated levels of inflammatory mediators, specifically IFNγ and TNFα." (PMID 30249047, 2018). "It has been proved that interleukin-10-knockout (IL-10 KO) mice display the most similar characteristics to that of human Crohn's disease (CD)." (PMID 28039475, 2017). "The first clinical study was completed in 2006 using L. lactis for secretion of human IL-10 in patients with Crohn’s disease." (PMID 27142045, 2016). "Some studies indicate that this receptor is crucial for the induction of IL-10 expression during fungal infection and in Crohn’s disease models." (PMID 27377650, 2016). "The first study was performed in the Netherlands and assessed LAB IL-10 effects in Crohn’s disease patients." (PMID 25889561, 2015). "A phase I clinical trial was then conducted with this biocontained L. lactis IL-10 strain in Crohn’s disease patients, showing that the containment strategy was effective." (PMID 25889561, 2015). "Patients with Crohn’s disease receiving higher doses of IL10 developed anemia and a dose-dependent increase of serum ferritin concentration." (PMID 23941335, 2013). "The clinical trail utilising IL-10 expressing L. lactis for the treatment of Crohn's disease has confirmed that such bacteria represent a viable approach for the mucosal release of therapeutically exciting proteins." (PMID 22315590, 2012). "The NOD2 3020insC mutation blocks p38 phosphorylation of hnRNP-A1, which impairs hnRNP-A1 binding to the IL-10 locus in peripheral blood mononuclear cells from Crohn’s disease patients." (PMID 23162548, 2012).
Crohn disease (continued). "The reduction of IL-10 production would lead to increased production of IL-12, thereby contributing to the excessive inflammation observed in Crohn’s disease patients." (PMID 23162548, 2012). "Some studies have reported that serum levels of IL-10 were increased in several inflammatory diseases, such as; Crohn’s disease, diffuse cutaneous systemic sclerosis and active Behçet's disease." (PMID 22393278, 2012). "For example, the chemical model induced by dextran sulfate sodium (DSS) display inflammatory features similar to ulcerative colitis, while in IL-10−/− the inflammation resembles Crohn's disease featuring transmural inflammation in colonic mucosa." (PMID 22400037, 2012). "Similar to the intestinal DCs in patients with Crohn's disease, murine IL-10-/- DCs produced more IL-1β than their wild-type counterparts and promoted Th17 cell development in an IL-1-dependent manner." (PMID 22176654, 2011). "Our work therefore demonstrates a potent cellular and molecular link between IL-10 and Th17 cells in mice and in humans with Crohn's disease." (PMID 22176654, 2011). "IL-10 has an anti-inflammatory role in the gut and the consumption of IL-10 producing transgenic bacteria has shown efficacy in the treatment of Crohn's disease." (PMID 20331905, 2010). "Nevertheless, IL‐10 has been described as a “context dependent” cytokine, since it may also act as an immunostimulatory cytokine in certain diseases such as cancer or Crohn's disease." (PMID 40901647, 2025). "We tested whether RF in IL-10−/− Sv129 mice restores the colonic clock and impacts their Crohn’s disease-like phenotype." (PMID 38918576, 2024). "Moreover, only one clinical trial with 10 patients with Crohn’s disease was included, which showed that L. lactis producing IL-10 was safe, and a decrease in disease activity was observed in these patients." (PMID 37049407, 2023). "In a previous study, B cells from patients with Crohn’s disease (CD) had significantly reduced IL-10 production induced by CpG DNA and were effective in the treatment of Crohn’s disease (CD) by adoptive transfer experiments after in vitro induction of IL-10+ Bregs." (PMID 35371051, 2022). "Similarly, the anti-inflammatory effect of Fusicatenibacter, particularly its F. saccharivorans species, has recently been demonstrated in patients and mouse models with ulcerative colitis and Crohn’s disease through IL-10 induction." (PMID 35983031, 2022). "Previous studies suggested that Interleukin‐10 (IL‐10) depletion in Crohn's disease (CD) could predict outcome." (PMID 36169258, 2022). "Interestingly, we found that this specific IL-10-inducing pathway was impaired in Crohn’s disease patients." (PMID 35169232, 2022). "Clinical trials for recombinant human IL-10 (Tenovil) found that patients with Crohn’s Disease (CD) who had high disease burden and low IL-10 levels could benefit from IL-10 supplementation." (PMID 36522454, 2022). "Defects in Il-10 signalling pathway manifest as a Crohn’s disease-like conditions." (PMID 33691712, 2021). "Increased levels of anti-inflammatory cytokine IL-10 in CβG− may be surprising; however, reports from clinical observations demonstrate a compensatory increase of IL-10 levels in patients with Crohn’s disease." (PMID 31590413, 2019). "Hypoxia significantly reduces tumor necrosis factor α, interleukin (IL)-6 and NLRP3 expression, and increases the turnover of the autophagy protein p62 in colon biopsies of Crohn’s disease patients, and in samples from dextran sulfate sodium-treated mice and Il-10−/− mice." (PMID 28740109, 2017). "Finally, the safety and efficacy of ex vivo expanded ovalbumin-specific IL-10-producing Treg has been assessed in patients with Crohn’s disease (CD)." (PMID 29123521, 2017). "Indeed, lamina propria mononuclear cells isolated from inflamed mucosa collected from patients with Crohn’s disease and ulcerative colitis produced less IL-10." (PMID 26549988, 2015).